PMS2 (PMS1 homolog 2, mismatch repair system component)
Diseases named in the same sentence as PMS2 in open-access papers (continued):
Sharing a sentence is not in itself a finding about the gene and the disease.
endometrial cancer (continued). "HNPCC patients with endometrial cancers have an inherited germline mutation in MLH-1, MSH-2, MSH-6, or PMS-2, but endometrial cancer only develops after the instauration of a deletion or mutation in the contralateral MLH-1, MSH-2, MSH-6, or PMS-2 allele." (PMID 20396392, 2010). "Notably, the prevalence of the MLH1-/PMS2- pattern was lower in endometrial cancer (69.2%) than in colorectal (81.1%) and gastric cancers (93.3%)." (PMID 37953261, 2023). "Additionally, the most prevalent cause of dMMR in endometrial cancer, MLH1 promoter methylation, results in the concurrent loss of MLH1 and PMS2 staining patterns in IHC." (PMID 37623510, 2023). "Patients with endometrial cancer found to be dMMR by IHC should be referred for MLH1 gene promoter hypermethylation (in case of MLH1/PMS2 loss) and/or germline testing regardless of results of MSI testing by molecular methods." (PMID 34145315, 2021). "The proband was diagnosed with three primary LS-associated tumors (one endometrial cancer at the age of 55 years and two CRCs (at the ages of 54 and 59 years), immunohistochemical analysis was available from the latter, which confirmed the decreased expression of MLH1 and PMS2)." (PMID 39827169, 2025). "There were no endometrial cancer patients with PMS2 mutations in this series." (PMID 32854222, 2020).
endometrial cancer (continued). "The proportion of MSH6/PMS2, where the non-endometrioid type with poor prognosis is found more frequently, appears to be high in endometrial cancer LS." (PMID 35884469, 2022). "We could not analyse PMS2 carriers, as the number of cases with non-colorectal/non-endometrial cancers (n = 7) was too low for further analysis." (PMID 30386444, 2018). "In endometrial cancer line HEC-1-A, PMS2 was observed lacking and defective in correcting a variety of mismatches and transfection of PMS2 caused these cells to increase microsatellite stability and repair of mismatches." (PMID 26036629, 2015).
breast carcinoma (79 papers, 2007 to 2025). "In terms of extra-colon cancer risk, germline mutations in MSH6 and PMS2 have been associated with increased risks of both breast cancer and ovarian cancer, with a doubling of the likelihood of developing breast cancer by the age of 60 years." (PMID 38473212, 2024). "Germline mutations in MSH6 and PMS2 genes occur more frequently in Lynch syndrome-related breast cancer, and their polymorphisms are related to breast cancer occurrence and progression." (PMID 39334297, 2024). "A recent research study showed that women with alterations in PMS2 gene have a 3-fold increased risk for breast cancer and 37.7% cumulative risk by the age of 60." (PMID 33503040, 2021). "In Caucasians, contradictory reports were published on the association of PMS2 gene mutations in breast cancer." (PMID 32959997, 2020). "Loss of each of the MMR proteins, except for PMS2, was significantly associated with the disease-specific death in ER+ breast cancers (p < 0.05)." (PMID 32098071, 2020). "In conclusion, our data demonstrate that PVs in MSH6 or PMS2 are associated with a modest but statistically significant increased risk for breast cancer." (PMID 29345684, 2018). "Our data demonstrate that two LS genes, MSH6 and PMS2, are associated with an increased risk for breast cancer and should be considered when ordering genetic testing for individuals who have a personal and/or family history of breast cancer." (PMID 29345684, 2018). "We observed that all colorectal-, gastric, endometrial-, prostate- and ovarian cancers and 2/3 of breast cancers occurring in carriers of the PMS2 mutation displayed MSI." (PMID 24790682, 2014). "Specifically, the first application is devoted to study the association between a single nucleotide polymorphism (SNP) and CRC in carriers of a pathogenic variant in the PMS2 gene while the second one focuses on the association of a 161 SNP‐based PRS with breast cancer." (PMID 40500950, 2025). "Many recent large-scale studies have published regarding this, including recent evidence that variants in the MMR genes MSH6 and PMS2 may be associated with an increased risk of breast cancer." (PMID 34439310, 2021). "However, there is insufficient evidence to prove that MLH1 and PMS2 are related to breast cancer risk and mutation carriers need to be managed based on family history." (PMID 34917121, 2021). "However, the association of PMS2 gene with breast cancer is still unclear." (PMID 32959997, 2020). "The nuclear DL model was validated for MSH6 in the colon, MSH6 and PMS2 in the endometrium, Ki-67 and CyclinB1 in prostate, and oestrogen and progesterone receptors in the breast cancer cohorts." (PMID 39040241, 2024). "Female carriers also have a higher lifetime risk of developing breast cancer compared to the general population depending on the specific gene mutation (MLH1, PMS2 etc.)." (PMID 39796639, 2024).
breast carcinoma (continued). "Although we did not have sequencing data available from the original tumor of patient #26, the #26 PDO had mutations typically present in breast cancer, such as mutations in BRCA2, FGFR2, and PMS2." (PMID 37423299, 2023). "In early-onset breast cancer, concurrent germline variants of BRCA1, BRCA2, PMS2, and PALB2 were reported." (PMID 37628631, 2023). "Five variants were in genes which have been reported to be associated with breast cancer risk in at least 50 manuscripts in PubMed (DST, CHEK2, FASN, TNN, and PMS2)." (PMID 38136396, 2023). "In a previous study, dMMR was observed in 0.4% (1/285) of breast cancer cases, which were TNBC cases with loss of MLH1 and PMS2 proteins." (PMID 33717059, 2021). "When evaluating by gene, only two of the four MMR genes were found to have a statistically significant increased association with breast cancer: MSH6 (SIR = 2.11; 95% CI, 1.56–2.86) and PMS2 (SIR = 2.92; 95% CI, 2.17–3.92)." (PMID 29345684, 2018). "By testing a sequential series of breast cancer patients for 25 cancer predisposition genes, Tung and colleagues identified carriers of mutations in the MSH6 and PMS2 genes." (PMID 28637432, 2017). "We also identified four mutations in MMR genes (PMS2 and MLH1), but in three of our four families, there were exclusively breast cancer pedigrees." (PMID 27779110, 2017). "Three breast cancers, one sarcoma, one prostate cancer and one renal cancer, all showed normal IHC for PMS2." (PMID 24790682, 2014). "Furthermore, immunohistochemical staining of a breast cancer sample harboring an MLH1 mutation revealed complete loss of MLH1 and PMS2 protein expression in tumor cells." (PMID 40281786, 2025). "Moreover, one breast cancer patient (BC310) with family history of stomach, colon and breast cancer, harbored a frameshift deletion in the PMS2 gene (c.2186_2187del)." (PMID 38313678, 2024). "Although already described in other tumors as a somatic variant, to the best of our knowledge, this PMS2 germline mutation has never been previously reported in breast cancer patients." (PMID 37783677, 2023).
breast carcinoma (continued). "Taken together, results presented here suggest that MLH1/PMS2 downregulation could constitute a first-in-class predictive marker for response to HER2 inhibition in endocrine-therapy-resistant ER+/HER2− breast cancer." (PMID 34011995, 2021). "In addition to the hereditary breast cancer susceptibility genes listed by NCCN, MLH1 and PMS2 are risk genes recommended by NCCN for multigene testing." (PMID 34917121, 2021). "Finally, we detected in a Caucasian female diagnosed with breast cancer at the age of 65 years partial skipping of PMS2 exon 1 (r." (PMID 32133419, 2020). "It has been observed that mutation in MSH6 and PMS2 increases the risk of breast cancer by 30% and 35%, respectively, irrespective of other personal cancer history." (PMID 33182707, 2020). "Previously, the identification of a PV in MSH6 or PMS2 in a woman with breast cancer may have been considered an incidental finding." (PMID 29345684, 2018). "This study suggests that women with PVs in MSH6 or PMS2 may benefit from increased breast cancer screening." (PMID 29345684, 2018). "Here we show that PVs in MSH6 or PMS2 are associated with breast cancer and that these MMR genes should be considered when ordering a multigene panel for women with a personal or family history of breast cancer." (PMID 29345684, 2018). "A protein truncate leading to deficiency of PMS2 caused a lack of repair function in breast cancer cells." (PMID 26036629, 2015). "In the first application, we focus on colorectal cancer (CRC) in carriers of the pathogenic variant PMS2, and in the second application, we analyze the association between a polygenic risk score (PRS) based on common breast cancer‐associated variants and breast cancer risk in multiple case families." (PMID 40500950, 2025). "While some studies report an increased risk of breast cancer in PMS2 and MSH6 carriers, this could not be validated in other cohorts." (PMID 39684258, 2024). "Interestingly, most of PMS2 PV carriers showed, beyond CRC, some cases of associated breast cancer, supporting the recent hypothesis that this neoplasm could also be included in the LS tumor spectrum, as already highlighted by other studies." (PMID 35223509, 2022). "However, several of our premenopausal breast cancer patients carried germline variants of unknown/uncertain significance (VUSs) in eight different breast cancer susceptibility genes, namely BRCA1, BRCA2, CHEK2, RAD51C, RAD51D, ATM, BRIP1, and PMS2." (PMID 36011273, 2022). "Defects in the MutL complex of mismatch repair, comprised of MLH1 and PMS2, were recently identified as drivers of endocrine treatment resistance in 15–17% of ER+/HER2− breast cancer patients." (PMID 34011995, 2021). "The carrier of the MUTYH variant, rs34612342, (OCE17-2) had a family history of skin and breast cancer and was a carrier of an additional VUS in the Lynch gene PMS2 as well." (PMID 28591191, 2017).